INS (insulin)
Diseases named in the same sentence as INS in open-access papers (continued):
Sharing a sentence is not in itself a finding about the gene and the disease.
metabolic syndrome (continued). "Indeed, it would be not surprising that an insulin resistant state on a background of genetic susceptibility to metabolic abnormalities worsens the expression of dyslipidemia." (PMID 25897955, 2015). "Decreased insulin sensitivity together with increased body weight are features that nicely resemble some of the key physiological effects of hypercortisolaemia as observed in people suffering from Cushing’s syndrome (excess of cortisol secretion) or the metabolic syndrome." (PMID 25310187, 2014). "Metabolic syndrome (MetS) is a cluster of disturbed glucose and insulin metabolism, obesity or abdominal adiposity, dyslipidemia, and hypertension." (PMID 24406665, 2014). "Thus, relatively large reductions in these fat compartments may be needed to achieve improvements in insulin sensitivity in older men with upper body obesity and components of the Metabolic Syndrome." (PMID 25392748, 2014). "In addition to insulin impairment, dyslipidemia or adiponectinemia might determine the neuropathy phenotype." (PMID 24764191, 2014). "Therefore, the use of omega-3 can be proposed as a VEGF antagonism and a novel pharmacological approach for metabolic syndrome and its components, targeting the lipid-transport properties of the endothelium to improve muscle insulin sensitivity and glucose disposal." (PMID 25136638, 2014). "Moreover, none of these variants were significantly associated with measures of adiposity, dyslipidemia or indices of insulin sensitivity or insulin secretion in a large cohort of non-diabetic, middle-aged Danish individuals." (PMID 24156295, 2013). "In their series of patients with RA the impaired insulin sensitivity was significantly associated with both low HDL cholesterol and high triglycerides, which are abnormalities that reflect the lipid component of atherogenic dyslipidemia observed in this chronic inflammatory disease." (PMID 23431244, 2013). "Chronic sympathetic nervous system overactivity contributes to a further decline of insulin sensitivity and creates a vicious circle that may contribute to the development of hypertension and of the metabolic syndrome and favor cardiovascular and kidney disease." (PMID 24288531, 2013). "Multiple consistent associations were observed between SNPs rs941798C/G and rs2426159A/G and metabolic parameters reflecting insulin sensitivity and the lipid profile, thereby suggesting that PTPN1 may influence susceptibility to the metabolic syndrome in a French population." (PMID 23762820, 2013). "By using global transcriptomic approaches, we set out to test the hypothesis that there would be changes in the expression of genes involved in inflammation, insulin signaling and mitochondrial function in the whole blood of the subjects classified with the metabolic syndrome." (PMID 24358323, 2013). "A decreased insulin sensitivity manifests itself in a reduced insulin-stimulated glucose uptake, reduced insulin-suppression of endogenous glucose production, reduced antilipolysis, decreased insulin-induced vasodilation, dyslipidemia, and platelet hyperaggregability." (PMID 23065486, 2012). "Otherwise, concomitant antihyperlipidemic agents such as fibrates and statins used in patients with dyslipidemia and insulins and insulin-release agents used in patients with DM may have controlled causal hypertriglyceridemia to such low levels that they do not trigger pancreatitis." (PMID 23300896, 2012). "In addition, further adjustment for metabolic syndrome or insulin in model 2 did not affect the association." (PMID 23316297, 2012). "Thus, in this paper, we presented evidence obtained from human primarily cultured omental preadipocytes as well as from metabolic syndrome patients and demonstrated that berberine improves insulin sensitivity by inhibiting fat store and adjusting the profile of adipokines." (PMID 22474499, 2012). "AS101 may influence the metabolic syndrome through interference in insulin pathways." (PMID 22761194, 2012).
metabolic syndrome (continued). "Furthermore, PL ameliorated dyslipidemia and hepatic steatosis through a combined decrease in hepatic lipogenesis and an increase in the excretion of fecal lipids, which seemed to be related to the enhanced responsiveness of the liver to insulin." (PMID 23145054, 2012). "The relationship between the RAAS system and insulin signalling pathways has led to the hypothesis that ANG II blockade (through use of ACEI and ARBs) in insulin resistant conditions such as the metabolic syndrome would be of benefit to metabolic and cardiovascular health." (PMID 22537670, 2012). "Therefore, CORMs may improve both cardiac mitochondria function and insulin sensitivity during metabolic syndrome." (PMID 22870253, 2012). "Importantly, compared with CON offspring, STZ offspring displayed more severe impairment in glucose tolerance test, and greater insulin insensitivity, dyslipidemia, and hepatosteatosis on HFD, while the metabolic dysfunctions were not obvious in STZ offspring on standard chow diets." (PMID 22566993, 2012). "It is known that visceral fat correlates better with the development of insulin insensitivity and the metabolic syndrome than does subcutaneous fat, and this may be related to the demonstrations that there is greater glucose uptake and insulin metabolism in visceral fat." (PMID 21647350, 2011). "This may suggest that lower insulin sensitivity is not linked to dyslipidemia in young MAs and/or that lower insulin sensitivity precedes the dyslipidemic phenotype, which has been previously observed in other studies." (PMID 21364957, 2011). "As medicines used to regulate glycemia and dyslipidemia are costly, the use of peppermint juice may be an alternative low-cost strategy to treat noncommunicable diseases associated with the insulin dysfunction." (PMID 21647314, 2011). "In addition, ghrelin levels did not correlate with insulin or glucose, indicating that regulation of ghrelin might be altered in obese patients with metabolic syndrome independently of insulin." (PMID 20798765, 2010). "Some organizations, thus, have proposed the "metabolic syndrome (MetS)," a constellation of simple clinical parameters with cut-off values, to find individuals who would probably be insulin resistant." (PMID 20846382, 2010). "Therefore, small molecules that could reduce insulin dependence and regulate dyslipidemia could have a dramatic effect on public health." (PMID 20811644, 2010). "Without an oral glucose tolerance test, fasting glucose and insulin measurements may fail to identify metabolic syndrome risk in children with Alström syndrome." (PMID 21274310, 2009). "Moreover, recent studies revealed that ligand activation of these receptors is associated with improved insulin sensitivity and elevated HDL levels thus demonstrating promising potential for targeting PPAR delta in the treatment of obesity, dyslipidemias and type 2 diabetes." (PMID 16168052, 2005). "In this context, LASSBio-1986 increased insulin sensitivity, enhanced GLUT-4 expression in skeletal muscle and attenuated dexamethasone-induced dyslipidemia, again underscoring the advantage of a multimodal profile." (PMID 41596477, 2026). "Notable examples of dual and pan-NR agonists include dual PPARα/γ agonists, such as saroglitazar and NET-144, which improve lipid profiles and insulin sensitivity, offering therapeutic benefits for conditions like T2DM, metabolic syndrome, and MASLD." (PMID 40926269, 2025). "Diet, exercise, and insulin-sensitizing pharmaceutical treatments like metformin, all of which activate AMPK, are being used to treat T2DM and the metabolic syndrome." (PMID 39791169, 2025). "This study examined seasonal changes in insulin, adiponectin, leptin, and HOMA-IR levels among healthy individuals and those with metabolic syndrome (MS) in Chiang Mai, Thailand." (PMID 40863890, 2025).
metabolic syndrome (continued). "A randomized clinical study found that berberine administration reduced metabolic syndrome, waist circumference, SBP, triglycerides, and total insulin secretion while increasing insulin sensitivity." (PMID 39817379, 2025). "Conversely, a loss of beneficial SCFA-producing bacteria (e.g., Faecalibacterium prausnitzii and Roseburia) is often noted in T2D and metabolic syndrome, potentially reducing SCFA-mediated benefits in insulin sensitivity and gut integrity." (PMID 40871736, 2025). "Moreover, increased free fatty acids (FFAs) release from adipose tissue disrupts insulin signaling, promotes hepatic glucose production, and activates cholesteryl ester transfer protein, thereby disrupting vascular homeostasis and, exacerbating atherogenic dyslipidemia and inflammation." (PMID 40727914, 2025). "This study evaluated the seasonal variation in insulin, adiponectin, leptin, and HOMA-IR levels among healthy individuals and those with metabolic syndrome (MS) in relation to ambient PM2.5 exposure in Chiang Mai, Thailand." (PMID 40863890, 2025). "C2 + % of pre‐hypertension, + levels of diastolic blood pressure, fasting insulin, HOMA‐IR, triglycerides and metabolic syndrome vs C3." (PMID 39967026, 2025). "In addition, when dietary saturated fatty acids are replaced with carbohydrates, MUFAs are efficient at maintaining high-density lipoprotein cholesterol levels, lowering triglyceride levels and enhancing insulin sensitivity, which could help people with metabolic syndrome or diabetes mellitus." (PMID 40805652, 2025). "Metabolic syndrome markers were worse in NAFLD, with elevated fasting insulin, triglycerides, and low-density lipoprotein (LDL), and lower high-density lipoprotein (HDL) (all p < 0.05)." (PMID 40970074, 2025). "Ehrmann et al15 similarly found high metabolic syndrome prevalence in women with PCOS, particularly women with higher BMI and insulin levels." (PMID 41171273, 2025). "Blood parameters in the whole cohort confirmed the presence of abnormalities in nutritional values predictive of metabolic syndrome, namely HDL, insulin and leucine." (PMID 39858651, 2025). "The results show that individuals with metabolic syndrome (WSM group) had significantly higher levels of BMI, waist circumference, plasma lipids (total cholesterol, LDL, triglycerides), glucose, insulin, and uric acid compared to the other groups." (PMID 40630388, 2025). "Although insulin and HDL-C outcomes were more variable, the overall findings support curcumin as a promising candidate for managing metabolic syndrome in preclinical settings." (PMID 40868165, 2025). "In human trials, several adult studies have reported transient improvements in metabolic profiles, such as insulin sensitivity, inflammatory markers, and GM composition, following FMT from lean donors in individuals with metabolic syndrome." (PMID 41010468, 2025). "Raising IL-1β, NF-kβ signaling, insulin, insulin resistance, FFAs, MGO, and AGEs leads to dyslipidemia and vascular complications." (PMID 39877627, 2025). "We demonstrated improvements in insulin kinetics, a decrease in liver fat, and a decrease in hepatic DNL together with correction of dyslipidemia." (PMID 40429553, 2025). "The author reported an increase in blood glucose, insulin, HOMA-IR, and changes in the lipid profile compatible with dyslipidemia after induction using an HFD with 60% fat for 91 days and the administration of 45 mg/kg of STZ i.p. in a single dose." (PMID 40426986, 2025). "The results showed, that after 12 weeks of ursolic acid intake (150 mg of ursolic acid/day), 50% of patients experienced a remission of metabolic syndrome, with significant improvements observed in FBG and insulin sensitivity." (PMID 38999920, 2024). "Studies conducted in rats with metabolic syndrome have shown that HBOT and exposure to mild hyperbaric oxygen improved insulin sensitivity and biochemical parameters of dyslipidemia." (PMID 39728298, 2024).
metabolic syndrome (continued). "Furthermore, increasing LAP values have been associated with atherogenic dyslipidemia (increased apoB levels, reduced LDL and HDL particle size) and insulin resistance, which in turn could lead to arterial stiffness and possibly coronary atherosclerosis progression." (PMID 39452286, 2024). "Insulin-resistant cells cannot respond to insulin and use glucose from the blood, a critical aspect responsible for developing T2DM and metabolic syndrome (MetS)." (PMID 38378663, 2024). "Analysis of the correlation of biochemical indicators of metabolic syndrome (triglycerides, HDL cholesterol, blood glucose, and insulin with the HOMA-IR index) with absolute concentrations of NAA and Cho in obese individuals showed interesting results." (PMID 39597065, 2024). "Further aggravation of disturbed insulin signaling in the presence of increasing ANGII, eventually leads to metabolic syndrome and T2D." (PMID 38323106, 2024). "Children in the consistently unhealthy group had increased odds of pre-hypertension and higher levels of diastolic blood pressure, fasting insulin, HOMA-IR, triglycerides, and metabolic syndrome score at 8 years of age." (PMID 38279175, 2024). "We reproduced a metabolic syndrome-like phenotype in B6J males and females fed an HFD characterized by increased fasting blood glucose and insulin resistance, as demonstrated by IPGTT." (PMID 39408267, 2024). "The blood work of these individuals indicate higher levels of TGs and insulin/glucose levels and lower levels of HDL cholesterol, which can lead to higher prevalences of metabolic syndrome." (PMID 39062264, 2024). "Significant increases in leptin, triglycerides, insulin, intra-abdominal fat, adipocyte area and HSL activity are found in a metabolic syndrome model of male Wistar rats." (PMID 38396865, 2024). "PGR was successfully used in adolescents and adults with metabolic syndrome and T2DM and successfully reduced circulating levels of insulin, lipids, and post-prandial triglycerides." (PMID 38891828, 2024). "As a marker for metabolic syndrome, ADP exhibited inverse correlation with WC, visceral fat, blood pressure, blood lipids, blood glucose, and insulin levels." (PMID 37853077, 2023). "In obese, human, metabolic syndrome recipients, allogenic fecal microbiota transfer (FMT) using metabolic syndrome donors (vs. post-gastric bypass donors) decreases insulin sensitivity, suggesting that dysbiosis can trigger MUO." (PMID 37396171, 2023). "Patients with liver steatosis showed a significant increase in BMI, diastolic pressure, insulin, HOMA index, glycated hemoglobin (HbA1c), C-reactive protein, triglycerides, fatty liver index (FLI), and the presence of metabolic syndrome." (PMID 38034016, 2023). "The quitters and the reducers tended to have high prevalence of hypertension, dyslipidemia, and CKD, accompanied with longer duration of DM, higher number of oral antidiabetic agents and more use of insulin than the sustainers." (PMID 37648711, 2023). "Thus, the effects of dietary ω-3 and ω-6 FFAs (or their ratios) on glucose homeostasis and metabolic syndrome may depend on their substrate effects to produce HODEs vs. HEPEs, rather than their systemic effects to alter other cellular functions (e.g., insulin secretion)." (PMID 37445935, 2023). "In our study, reducers and quitters had higher prevalence of hypertension, dyslipidemia, and CKD, accompanied with longer duration of DM, higher number of oral antidiabetic agents and more use of insulin, compared to sustainers." (PMID 37648711, 2023). "The mechanisms involving dyslipidemia and CKD are not yet fully understood, but it is possible to highlight some more relevant factors such as insulin resistance and increased oxidative stress." (PMID 37089474, 2023). "Therefore, dyslipidemia is the outcome of insulin action but is not a risk factor." (PMID 37033225, 2023).
metabolic syndrome (continued). "Desulfobacteriacea was negatively correlated with characteristic features of IR (HOMA-IR and insulin levels), increased abdominal obesity (weight, BMI, WC percentile, and HC), hypertension (SBP percentile), and dyslipidemia (HDL levels)." (PMID 37342535, 2023). "Improved insulin action by GLP-1RA can play a crucial role in ameliorating both glycemia and dyslipidemia." (PMID 36979848, 2023). "As a consequence, T1DM is characterized by the reduction of several hormones released by beta cells (e.g., insulin, amylin, C-peptide), whereas T2DM is characterized by glucose-independent metabolic abnormalities (dyslipidemia)." (PMID 37959313, 2023). "Significant differences (p < 0.05) between groups were observed for BMI, diastolic pressure, insulin, HOMA index, glycated hemoglobin (HbA1c), C-reactive protein, triglycerides, fatty liver index – FLI, and the presence of metabolic syndrome." (PMID 38034016, 2023). "The mean insulin and HOMA-IR index in our patients with metabolic syndrome were 20.8±4.3 mU/mL and 5.8±1.3, respectively." (PMID 37809190, 2023). "Several studies demonstrated that VAI was the best predictor of metabolic syndrome and IR in PCOS women, while others indicated that WHR was also a useful insulin sensitivity predictor." (PMID 37630842, 2023). "Patients with metabolic syndrome following a 10-h TRF also demonstrated reductions in body weight and improvements in glycemia (reduced HbA1c, plasma glucose/insulin levels and HOMA-IR)." (PMID 35215472, 2022). "Currently there are no FDA-approved single agent treatments for the concurrent management of insulin sensitivity and the prevention (or at least the attenuation of progression to) to NAFLD/NASH in individuals with metabolic syndrome and T2D." (PMID 35831885, 2022). "Pearson’s correlations were used to assess the correlations between PHQ-9 and GAD-7 scores with the metabolic syndrome biomarkers of glucose, triglycerides, HDL cholesterol, and insulin." (PMID 36404332, 2022). "Since then, more researchers have studied the effects of myo-inositol and its role in increasing insulin sensitivity in such diseases as PCOS, GDM, T2DM and metabolic syndrome in women during the postmenopausal period." (PMID 35794663, 2022). "A short-term decrease of SOCS3 in the liver improves insulin sensitivity; however, long-term suppression of SOCS3 induces metabolic syndromes such as hyperglycemia and obesity." (PMID 35626153, 2022). "After four weeks of supplementation, only the new nutraceutical group (HFD + Supplemented) experienced reduced fasting glycemia, insulin, HOMA index, HOMA-β, dyslipidemia, ectopic fat deposition, and hepatic fibrosis levels." (PMID 35326098, 2022). "Importantly, some gut microbes associated with improved insulin sensitivity and recovery from metabolic syndrome only appeared in amoxicillin-treated HFD-fed mice reinforcing the beneficial effects of antibiotic treatment in the HFD-associated metabolic syndrome." (PMID 36229889, 2022). "These preclinical investigations have shown that after 4 weeks of supplementation, the new nutraceutical reduced fasting glycemia, insulin, HOMA-IR, HOMA-β, dyslipidemia, ectopic fat deposition, and hepatic fibrosis levels." (PMID 36778595, 2022). "However, the current study observes associations between number of CLS and pro-inflammatory cytokines, adiponectin and HOMA2-IR scores suggesting a more pro-inflammatory environment is associated with insulin signalling even in the absence of enhanced fibrosis and metabolic syndrome." (PMID 35958557, 2022). "Hepatic insulin clearance (HIC) is a novel and important pathophysiological mechanism of hyperinsulinemia, metabolic syndrome, and T2DM; hepatic insulin clearance is decreased in these metabolic conditions." (PMID 35115614, 2022). "The researchers have demonstrated increased serum C-peptide, reflecting raised insulin secretion, is as a biomarker for obesity and insulin resistance, especially in T2DM and metabolic syndrome (MS)." (PMID 35609059, 2022).